USP17L26 (ubiquitin specific peptidase 17 like family member 26)
Description:
Deubiquitinating enzyme that removes conjugated ubiquitin from specific proteins to regulate different cellular processes that may include cell proliferation, progression through the cell cycle, apoptosis, cell migration, and the cellular response to viral infection.
Target class: Enzyme; Hydrolase
Gene: Protein-coding gene on chromosome 4 (9,334,658 to 9,336,250, forward strand). Ensembl gene ENSG00000229579.
Subcellular location: Nucleus, nucleolus; Endoplasmic reticulum
Pathways (Reactome):
Metabolism of proteins: Ub-specific processing proteases
Gene Ontology:
Molecular function: cysteine-type deubiquitinase activity; hyaluronic acid binding; RNA binding
Biological process: positive regulation of epithelial cell apoptotic process; protein deubiquitination involved in ubiquitin-dependent protein catabolic process; regulation of apoptotic process; protein deubiquitination
Cellular component: nucleolus; nucleus; endoplasmic reticulum
Homologues: Paralogues in human: USP17L24 (100% identical), USP17L25 (100% identical), USP17L27 (100% identical), USP17L28 (100% identical), USP17L29 (100% identical), USP17L30 (100% identical), USP17L5 (99% identical), USP17L20 (99% identical), USP17L11 (99% identical), USP17L17 (99% identical), USP17L18 (99% identical), USP17L22 (99% identical), and 59 more.
Diseases named in the same sentence as USP17L26 in open-access papers:
USP17L26 is named in the same sentence as 1 disease in open-access papers, as found by Europe PMC text mining. Sharing a sentence is not in itself a finding about the gene and the disease.
USP17L26 shares sentences with these, for which no sentence is quoted: viral infection (1 paper).